TPX2 (TPX2 microtubule nucleation factor)
Diseases named in the same sentence as TPX2 in open-access papers (continued):
Sharing a sentence is not in itself a finding about the gene and the disease.
cancer (continued). "The TPX2 (targeting protein for xenopus kinesin-like protein 2), a microtubule-associated protein involved in spindle formation and cell division, is highly expressed in various cancers, including BC." (PMID 37370847, 2023). "Tpx2, in addition to regulating the mitotic spindle, plays an important role in cell-cycle kinase Aurora A activation, and its overexpression is associated with the development of various cancers." (PMID 38077941, 2023). "In this study, we performed the gene set enrichment analysis of TPX2 in 33 types of cancers and an extensive pan-cancer bioinformatic analysis using prognosis, tumor mutational burdens, microsatellite instability, tumor microenvironment, and immune cell infiltration data." (PMID 36304254, 2022). "Recent technological advances in DNA sequencing have enabled a more detailed understanding of the molecular changes that define gynecological tumors, and the association between TPX2 overexpression and copy number amplification has been reported in malignant tumors of the ovaries and cervix." (PMID 35356748, 2022). "The process through which TPX2 depletion causes cancer cells to die is unclear; however, it might involve mitotic disruption." (PMID 36304254, 2022). "TPX2 has been considered as an important regulator of human cancers or a promising therapeutic target for treatment, and overexpression of TPX2 is associated with the progress of human malignancies or the poor prognosis of human patients, especially those with PC." (PMID 34123781, 2021). "TPX2 is a tubulin-associated protein considered as a proto-oncogene in human cancer cells." (PMID 34123781, 2021). "Over expression of microtubule associated protein TPX2 stimulates the cell cycle in cancer, but this gene might be activates cell cycle in pituitary prolactinoma." (PMID 33709028, 2021). "Ultimately, TPX2 was associated with cancer-related signaling pathways including “cell cycle”, “RNA degradation”, “mismatch repair”, “DNA replication”, “base excision repair”, “endocytosis”, “Notch signaling pathway” “PPAR signaling pathway” and “ERBB signaling pathway” (all p <0.05)." (PMID 33029085, 2020). "Beyond TPX2 amplification, elevated protein levels of TPX2 are frequently reported in cancer, although these effects may be indirectly caused by high levels of proliferation, since TPX2 is post-translationally regulated during the cell cycle." (PMID 30177840, 2019). "Similarly, in previous studies, genes that are closely associated with the mitotic spindle, such as survivin and TPX2, have been identified as markers for the diagnosis and prognosis of cancer." (PMID 26871431, 2016). "TPX2 targeting siRNAs caused cell cycle arrest and apoptosis in cancer cell lines." (PMID 22303466, 2012). "Altogether, our observations support the targeting of the Aurora-A/TPX2 complex as a promising strategy for the development of novel anti-cancer therapeutics." (PMID 41876446, 2026). "This study investigates the potential of BCL9 and TPX2, two proteins involved in cancer progression, to predict patient outcomes This study analyzed protein abundance data from the CPTAC cohort (110 ccRCC and 84 NAT samples) using LC-MS/MS." (PMID 40362354, 2025). "The coexpression of TPX2 with PD-L1 also has implications for immune evasion and cancer progression." (PMID 40508156, 2025). "As a key regulator in mitotic spindle assembly, TPX2 has been extensively studied in the context of mitotic fidelity and genome instability in cancer." (PMID 40362354, 2025). "For instance, TPX2, a hub gene in all three cancers, is known to play a crucial role in normal spindle assembly during mitosis and is essential for cell proliferation." (PMID 41404730, 2025). "The aberrant expression of TPX2 has been found in various cancers and is closely correlated with overall survival in cancer patients." (PMID 40107714, 2025).
cancer (continued). "More than ten years ago, we highlighted the frequent co-overexpression of AurkA and TPX2 in cancer, and proposed that it holds oncogenic potential, resulting in the formation of an oncogenic holoenzyme." (PMID 39195284, 2024). "Our analysis establishes a solid foundation for exploring TPX2 as a promising target in cancer therapy." (PMID 38315450, 2024). "HMMR’s association with key cell cycle regulators (AURKA, TPX2, and CDK1) underscores its pivotal role in cancer initiation and advancement." (PMID 38576486, 2024). "Our study demonstrated that TPX2 mRNA level was significantly upregulated in many types of cancers including LUAD." (PMID 38315450, 2024). "TPX2 overexpression stimulated cancer cell proliferation, promoted the G0‐G1‐to‐G2/M transition, enhanced invasion and migration, and accelerated tumor growth in nude mice." (PMID 38466034, 2024). "Overexpression of TPX2 was found in 22 types of cancers, and was positively related with copy number variations (CNV) and negative with methylation." (PMID 38315450, 2024). "TPX2 expression and macrophage M1 infiltration were positively correlated in 17 cancer types, but negatively in THYM." (PMID 38315450, 2024). "Particularly, some cancers showed different expression levels of TPX2 between stage I and IV underscoring pivotal roles of TPX2 in the development of cancers." (PMID 38315450, 2024). "According to Cox regression and Kaplan-Meier analyses, upregulation of TPX2 correlated with an adverse prognosis in most cancers." (PMID 38315450, 2024). "The expression pattern of TPX2 across different cancer types was explored using the SangerBox portal." (PMID 38833082, 2024). "A biomarker study involving 165 BC patient samples analyzed the expression levels of four genes (CCNB1, KIF4A, TPX2, and TRIP13) and their association with clinical characteristics, revealing a correlation between elevated CCNB1 expression and cancer stage." (PMID 39795587, 2024). "We found that DNA methyltransferases and MMRs genes were positively correlated with TPX2 in almost all cancer types." (PMID 38315450, 2024). "Our work delivers a holistic, pan-cancer view, bringing forth insights into TPX2’s role across an array of cancers, potentially highlighting commonalities and disparities among different cancer types." (PMID 38315450, 2024). "A negative correlation was observed between TPX2 methylation and TPX2 expression across multiple human cancers." (PMID 38315450, 2024). "Genomic alteration of TPX2 was common in different types of tumors, while with prognostic value in two types of cancers." (PMID 38315450, 2024). "Despite the frequent occurrence of AurkA/TPX2 co-overexpression in cancer, the investigation of their involvement in tumorigenesis and cancer therapy resistance mostly arises from studies focusing only on one at the time." (PMID 39195284, 2024). "It demonstrated the inhibitory potential of FDA-targeted cancer drugs on the TPX2–AURKA interaction, aiding the experimental investigators to develop targeted therapeutic strategies and improve clinical outcomes." (PMID 37768502, 2024). "In liver, ovarian, breast and other cancers, overexpression of TPX2 can activate the PI3K/Akt pathway." (PMID 38466034, 2024). "The expression of TPX2 in cancer tissues was significantly higher than that in adjacent normal tissues." (PMID 38466034, 2024). "Since their identification, AurkA and TPX2 have been described as being overexpressed in cancer, with a significant correlation with highly proliferative and aneuploid tumours." (PMID 39195284, 2024). "We used CancerSEA to investigate the correlation of TPX2 with 14 cancer functional states at the single-cell resolution." (PMID 38315450, 2024). "The rates of positive and strong positive TPX2 expression were significantly higher in cancer tissues, including those of endometrioid cancer, serous cancer and clear cell cancer, than in the corresponding normal endometrial tissues (p < 0.001)." (PMID 38466034, 2024).
cancer (continued). "We analyzed 190 single-cell datasets of cancer samples in order to identify the main cell types expressing TPX2 in the cancer microenvironments." (PMID 38315450, 2024). "We found that TPX2 expression correlated significantly with chemokine and chemokine receptor in almost all cancer types." (PMID 38315450, 2024). "Most cancer types exhibit TPX2 amplification patterns, particularly in UCS, which had more than 20% mutations with TPX2 amplification." (PMID 38315450, 2024). "Evidence suggests that TPX2 is frequently upregulated in malignancies and related to cancer progression." (PMID 38466034, 2024). "TPX2 upregulation and dependency across various aggressive cancers make it an attractive target for cancer therapies." (PMID 38660563, 2024). "Significantly elevated expression of TPX2 was observed in all cancer types, indicating that TPX2 has a potential oncogenic role." (PMID 38833082, 2024). "Increasing evidence has demonstrated the close involvement of TPX2 in multiple malignant tumors (such as esophageal, prostate, lung, breast, and gastric cancers)." (PMID 38833082, 2024). "TPX2 participates not only in chromosomal missegregation and aneuploidization but also in genomic instability, resulting in cell cycle progression in cancer cells." (PMID 38466034, 2024). "There were 22 tumors with higher expression of TPX2 than in the corresponding non-carcinoma tissues." (PMID 38315450, 2024). "It has been demonstrated that TPX2 is overexpressed in several cancers and highly expressed in CRC tissues." (PMID 37457582, 2023). "Targeting protein for Xenopus kinesin-like protein 2 (TPX2) is an indirect target of miR-485-3p prediction and has an important part in mitotic spindle assembly and cancer progression." (PMID 37457582, 2023). "Together, our results suggest that AURKA/TPX2 co-overexpression in cancer has an impact not only on mitotic but also on interphasic nuclear AurkA oncogenic functions." (PMID 36797043, 2023). "A recent study demonstrated that the Hedgehog signal is responsible for TPX2 induction through the FOXM1 transcription factor in cancer cells." (PMID 36596852, 2023). "We propose that AURKA/TPX2 co-overexpression in cancer represents a key determinant of AurkA nuclear oncogenic functions." (PMID 36797043, 2023). "cRTC contains a nanobody against an intrinsically disordered protein TPX2, a microtubule nucleation factor overexpressed in various cancers." (PMID 36964170, 2023). "It was found that POLE2, GABARAPL1, PIK3R1, NDC80, and TPX2 play critical roles in the response and overall survival in cancer patients under PD-L1 inhibitor treatment." (PMID 37240068, 2023). "When we analysed the cancer-specific genes like Cdc20, Hmmr, Tpx2, Cenpf, Birc5, Ube2c, Foxm1,Pold4, Nup210, Cenpm and Orc1, these pro-carcinogenic genes found to be over expressed in the disease control group." (PMID 36650455, 2023). "Here, we have used CRISPR genomics to identify the Aurora A activator TPX2 and kinetochore protein NDC80 as key components explaining the cancer-associated PPP6C loss-of-function phenotype." (PMID 36897279, 2023). "Highest enrichment was for genes in SPINK1 General Cancer and the Kinetochore Metaphase Signaling Pathway, which would be concordant with the known role for TPX2 in mitosis." (PMID 37770979, 2023). "Targeting protein for Xenopus kinesin-like protein 2 (TPX2) also functions as an oncogene in different human cancers." (PMID 35395834, 2022). "In this study, we discovered a correlation between TPX2 overexpression and poor prognosis among most cancers." (PMID 36304254, 2022). "TPX2 was previously studied as a regulator of mitotic spindle formation and shown to act as an inhibitory factor in various cancers, such as lung cancer, renal cancer, colon cancer, and glioma." (PMID 35273149, 2022). "In this study, we also found that TPX2 expression is highly correlated with multiple checkpoint molecules in multiple cancer types." (PMID 36304254, 2022).
cancer (continued). "We proposed that TPX2 can be used as a prognostic biomarker and therapeutic target for a variety of cancers." (PMID 36304254, 2022). "Our findings suggest a correlation between TPX2 overexpression and poor prognosis among most cancers and the potential for it to be used as an important target in antitumor metastasis therapy, which is conducive to precision medicine, for most malignancies." (PMID 36304254, 2022). "In most cancer types, TPX2 expression levels were found to be negatively correlated with stromal and immune cell contents, but the opposite was true for KIRC and THCA." (PMID 36304254, 2022). "This comprehensive pan-cancer analysis shows that TPX2 is a prognostic molecular biomarker for most cancers and suggests its potential as an effective therapeutic target for the treatment of these diseases." (PMID 36304254, 2022). "According to the differential expression study, TPX2 was found to be overexpressed across all studied cancer types." (PMID 36304254, 2022). "Our study is aimed at elucidating the role of TPX2 in cancer metabolism and immunity by performing a pan-cancer analysis of integrated multiomics data." (PMID 36304254, 2022). "We next divided the cancer samples into two groups based on high or low TPX2 expression levels and used GSEA to identify the enrichment of GO and KEGG gene sets in the two groups." (PMID 36304254, 2022). "Although TPX2 is highly expressed in several malignant tumor forms, little is known about its role in cancer." (PMID 36304254, 2022). "Although previous studies have shown that TPX2 can promote cancer cell proliferation and act as an unfavorable factor in many cancers, we found that low TPX2 levels in CD8+ T cells indicate compromised antitumor immunity in HCC." (PMID 35273149, 2022). "In line with the idea that cancer cells with pathogenic BRCA mutations depend on TPX2, knockdown of TPX2 has been reported to lead to HR defects and reduced viability of BRCA2-deficient cancer cells." (PMID 36350633, 2022). "It has been reported that TPX2 is overexpressed in many types of cancer, which is correlated with poor prognosis." (PMID 34257537, 2021). "Several high profile cases have identified TPX2 as an oncogene that promotes cancer proliferation and tumorigenesis." (PMID 32723329, 2020). "The overexpression of TPX2 is related to the genesis of different cancers and is closely related to chromosome instability." (PMID 32626756, 2020). "In live cancer, TPX2 inhibited the expression of MMP2 and MMP9 to suppress cell invasion and metastasis." (PMID 33098235, 2020). "TPX2 overexpression is frequently observed in cancer and high levels of TPX2 were shown to display the highest association score with chromosomally unstable tumours." (PMID 32041138, 2020). "Elevated expression of TPX2 is a common finding in human cancers, including prostate, and overexpression in vitro increases invasion of multiple cancer cell lines." (PMID 30616540, 2019). "For example, TPX2, a microtubule-binding protein, is a hub gene in all 8 cancer types, while EXO1 and BUB1 are hub genes in 5 cancer types." (PMID 31179925, 2019). "Altogether, our data indicate that BRCA2 inactivation renders cancer cells dependent on the TPX2/Aurora-A signaling axis for their survival." (PMID 30177840, 2019). "TPX2 is overexpressed in numerous types of cancer, and TPX2 expression level correlates with poor prognosis." (PMID 31272499, 2019). "Firstly, we used Oncomine database which covers 8603 genes in 203 cancer samples, and we identified TPX2 as the top gene with best correlation with TOP2A, R value = 0.862." (PMID 31528121, 2019).
cancer (continued). "Our findings reveal that BRCA2-deficient cancer cells show enhanced sensitivity to inactivation of TPX2 or its partner Aurora-A, which points at an actionable dependency of genomically unstable cancers." (PMID 30177840, 2019). "In the carcinoma cells, TPX2 staining was mainly found in the nuclei, while MMP12 expression was mainly observed in the cytoplasm of tumor cells." (PMID 30305064, 2018). "Using immunostaining, multiple studies reported that TPX2 is mainly localized within the nuclei of cancer cells." (PMID 28069036, 2017). "The latest finding that TPX2 plays a role in amplification of the DNA damage response, combined with the characterization of TPX2 knockout mice, provides a new perspective in understanding the signaling roles of TPX2 as they relate to cancer therapies." (PMID 27777511, 2016). "TPX2 over-expression occurs in various malignant tumors, resulting in abnormal cell centrosome amplification, aneuploid cell formation, and malignant transformation." (PMID 27777511, 2016). "Overexpressed in cancers, TPX2 is regarded as a novel candidate target for the diagnosis and prognosis of malignancies." (PMID 27777511, 2016). "TPX2, a protein involved in mitosis, is considered a good marker for actively proliferating tissues, highly expressed in a number of cancer cells." (PMID 25401333, 2014). "TPX2 has verified to be overexpressed in various human cancers including lung, colon, and bladder cancer." (PMID 25302620, 2014). "Several studies have demonstrated that TPX2 is overexpressed in different types of human cancers and promotes tumor growth and metastasis." (PMID 25302620, 2014). "Cancer cells in which TPX2 levels have been suppressed by small interfering RNAs are more sensitive to the microtubule stabilizing cancer drug paclitaxel." (PMID 23785665, 2013). "In experiment, withanone treatment to cancer cells indeed resulted in dissociation of TPX2-Aurora A complex and disruption of mitotic spindle apparatus proposing this as a mechanism of the anticancer activity of withanone." (PMID 22303466, 2012). "TPX2 knockdown by siRNA indeed resulted in increased survival of cancer cells subsequent to the treatment with i-Extract." (PMID 22303466, 2012). "Among them, the key spindle formation regulator Aurora-A and TPX2 co- expression were observed in increased abundance in several cancer types." (PMID 22956898, 2012). "Previously, we identified TPX2 as a cellular target for withanone that selectively kill cancer cells." (PMID 22303466, 2012). "For example, the apoptotic regulator BCL2L1, adjacent to TPX2, has been previously suggested as a 20q11 amplification target in cancer." (PMID 21103391, 2010). "TPX2 was overexpressed 15-fold in carcinomas and provides a possible mechanism for increased activation of Aurora-A kinase." (PMID 19077237, 2008). "TPX2 has been explored as a potential therapeutic target across multiple cancer types." (PMID 40362354, 2025). "TPX2 lactylation is required for the cell cycle regulation and cancer progression." (PMID 40107714, 2025). "Because inhibition of lactate production may have a broad effect, considering the critical role of TPX2 lactylation in cancer progression, further work will be required to generate inhibitors that could specifically suppress TPX2 K249 lactylation." (PMID 40107714, 2025). "Conversely, lower TPX2 levels are associated with significantly improved overall survival, despite no observed changes in perceptible cancer-related symptoms." (PMID 40362354, 2025). "Pixuvri’s multitarget approach, which targets proteins like BubR1, Cdc20, MAD2, and TPX2, could circumvent these resistance mechanisms, offering a more effective strategy against drug-resistant cancers." (PMID 40519296, 2025). "The majority of cancers in our study showed up-regulation of TPX2 at mRNA and protein levels." (PMID 38315450, 2024). "TPX2 expression was positively related to neoantigens in 10 cancer types, but negatively in COAD." (PMID 38315450, 2024).